UCP2 (uncoupling protein 2)
Diseases named in the same sentence as UCP2 in open-access papers (continued):
Sharing a sentence is not in itself a finding about the gene and the disease.
diabetes (94 papers, 2003 to 2025). "Collectively, we conclude that genetic polymorphisms in UCP2 increase the risk of type 2 diabetes mellitus." (PMID 39707176, 2024). "In this present study, the allele C was found to be the risk allele, similar to a study in Brazil which examined the association of this UCP2 variant with type 2 diabetes mellitus and diabetic retinopathy." (PMID 39561140, 2024). "Two genes were very proximal to each other located on chromosome 17p13.3 ‐ rs12150053 near SERPINF1 and rs659366 near UCP2, suggesting a possible hotspot related to susceptibility to type 2 diabetes mellitus in the region." (PMID 39561140, 2024). "Peritoneal glucose overload, old age, diabetes, and genetic polymorphisms, such as the uncoupling protein 2 exon 8 insertion/deletion, are known as risk factors for weight gain." (PMID 37432308, 2023). "Collectively, in stressed β-cells under diabetes, mitochondrial dysfunction caused by elevated UCP2 induced oxidative stress, resulting in activation of HNF4α and thus leading to the elevation of AldB expression." (PMID 35800776, 2022). "A study conducted in patients with diabetes from Scandinavia and healthy UK residents revealed a link between the allelic variants of Ucp3 –55C and Ucp2 Ins and a higher level of ACE activity in the blood plasma." (PMID 32450815, 2020). "A number of previous studies have studied rs660339 and rs659366 of UCP2 associated with diabetes and the results are contradictory." (PMID 29529994, 2018). "In a Finnish diabetes prevention study, three variants in the UCP2 gene, one variant in the UCP2-UCP3 intergenic region, and five variants in the UCP3 gene were explored." (PMID 23841103, 2013). "Diabetes is associated with increased oxidative stress and diabetic patients with the UCP2-866AA genotype and CHD have been shown to have lower total antioxidant status and higher levels of plasma F2-isoprostanes." (PMID 19527523, 2009). "UCP2 gene polymorphisms are strongly associated with the development of diabetes." (PMID 40686867, 2025). "Recent data suggest differences UCP2 expression driven by common polymorphisms in the UCP2 promoter region may play a critical role in insulin secretion and ultimately the development of diabetes." (PMID 31706320, 2019). "Whether UCP2 and PPARγ polymorphisms have an effect on inflammation state in diabetes remains unknown." (PMID 29849618, 2018). "Whether there is some interaction between UCP2 gene-defined risk and risk of diabetes requires some further investigation." (PMID 27615599, 2016). "Thus, UCP2 disturbances can be related to the causes and complications of type 2 diabetes mellitus, both related to increased ROS production." (PMID 23537071, 2013). "Polymorphisms in the UCP2 gene have been associated with obesity, hypertension, and diabetes." (PMID 19527523, 2009). "The distribution and frequency of these UCP2 gene polymorphisms may vary among different populations and can affect susceptibility to pancreas-related diseases, such as insulin secretion and type 2 diabetes mellitus, differently in various individuals and genders." (PMID 39707176, 2024). "Furthermore, maternal obesity and diabetes have been identified as risk factors of CHDs, which indirectly indicated that genetic variants of UCP2 may be associated with the risk of CHDs in offspring." (PMID 33888769, 2021). "Thus, UCP2 has been studied for its protective effects on several diseases associated with increased oxidative stress, including Alzheimer’s disease, Parkinson’s disease, arteriosclerosis, diabetes mellitus." (PMID 34829617, 2021). "The aim of this study was to investigate variants in UCP2 genes in type 2 diabetes mellitus (DM) and diabetic retinopathy (DR) in Chinese population." (PMID 25396419, 2014). "UCP2 dampens ROS generation and subsequent metabolic defects, including diabetes mellitus, atherosclerosis, and cardiomyopathy." (PMID 39596006, 2024).
diabetes (continued). "In the last part of this study, it was shown that induction of diabetes with a HFD led to a decrease in UCP2 level and oxidative stress, which were exacerbated in the concomitant presence of diabetes and menopause." (PMID 38134189, 2023). "In diabetic mice, capsaicin administration likewise alleviated diabetes-induced endothelial dysfunction—an effect negated by UCP2 knockout." (PMID 36135209, 2022). "Further studies are required to clarify the factors that determine UCP2 expression during the development of diabetes." (PMID 35800776, 2022). "Herein, UCP2 was found to be upregulated in IUGR piglets, suggesting that compared to NBW, IUGR animals are at a higher risk of developing diabetes." (PMID 36421816, 2022). "UCP2 is most widely present and highly expressed among UCPs in diabetic pancreatic beta-cells; therefore, its involvement in diabetes development has been proposed." (PMID 35323702, 2022). "In summary, we provide evidence that the upregulation of UCP2 in stressed β-cells under diabetes decreased insulin secretion due to mitochondrial dysfunction and impairment of Ca2+ release from the ER by inducing AldB expression." (PMID 35800776, 2022). "Increased mitochondrial UCP-2 expression in renal proximal tubular cells increased O2 consumption and reduced O2 availability which subsequently contributed to diabetes-induced progressive kidney damage." (PMID 34580604, 2021). "This study aimed to investigate the association of 45-bp ins/del polymorphism of UCP2 with susceptibility to NAFLD (Non-Alcoholic Fatty Liver Disease) and T2DM (Type 2 Diabetes Mellitus)." (PMID 33957975, 2021). "Consistently, previous studies have demonstrated that downregulation of UCP2 exacerbated oxidative stress damage as well as diabetes or HG-induced renal tubular epithelial cells apoptosis." (PMID 34580604, 2021). "Specifically, for the insulin-sensitive Glut-4, an inverse regulation between UCP-2 and Glut-4 was reported several times in skeletal muscles that were impaired by diabetes." (PMID 32120777, 2020). "For themeta-analysis, a literature search was conducted to identify all studies thatinvestigated associations between UCP2 polymorphisms and DKD inpatients with T1DM or type 2 diabetes mellitus." (PMID 31479096, 2020). "Uncoupling protein-2 (UCP2) has been held responsible for the diabetes-related uncoupled respiration in renal proximal tubular cells and in mitochondria isolated from the kidney cortex." (PMID 31195596, 2019). "Increased vascular expression of UCP2 in the setting of diabetes appears to be an initial compensatory response to systemic elevations in glucose that disappears over time with more chronic and severe abnormal glucose exposures on the diabetic endothelium." (PMID 31706320, 2019). "Most of the studies about the role of UCP2 in diabetes have focused on the UCP2 functions in β-cells, and the results have shown a deleterious effect of UCP2 in diabetes." (PMID 29949946, 2018). "As there are contrasting results on the biochemical and physiological functions of UCP-2, further clarification of the role of UCP-2 in the lipotoxicity of beta-cells and the pathogenesis of diabetes is needed." (PMID 30061862, 2018). "The functional benefit of uncoupling protein induction in diabetes is also supported by the finding that overexpression of UCP3 (that functions similarly to UCP2 but shows distinct expression profile) is protective against glucose-induced damage in neurons." (PMID 27128320, 2016). "Modulation of UCP2 was recommended in diabetes complications, since the induction of UCP2 expression is safe: the function of the protein is further controlled at the posttranslational level and it also occurs as an endogenous protective mechanism." (PMID 27128320, 2016). "GDP, an UCP2 inhibitor, increased mitochondrial membrane potential and superoxide production in controls and at 45 days of diabetes." (PMID 25951172, 2015).
diabetes (continued). "The ∆ψ increased in response to GDP in both the normal and the 45 day-diabetes, signifying that mitochondria from normal retina have an active UCP2, which was recovered at the 45 day-diabetic stage." (PMID 25951172, 2015). "The physiological functions of UCPs have long been debated since the new UCPs (UCP2 to 5) were discovered, and the role of UCPs in the pathogeneses of diabetes mellitus is one of the hottest topics." (PMID 23841103, 2013). "In conclusion, mitochondrial uncoupling via UCP-2 regulates mitochondria membrane potential in diabetes." (PMID 22768304, 2012). "UCP2 has been said to act as adiposity angel and diabetes devil, whereas increased expression of UCP3 has been suggested to be associated with weight loss success." (PMID 19769793, 2009). "Whole-body partial inhibition of UCP2 expression by antisense oligonucleotide treatment reversed hyperglycemia in models of diabetes and insulin resistance." (PMID 19065272, 2008). "We observed a similar increase in UCP-2 protein when cells were cultured at the presence of 11 mM glucose for 24 hr, glucose concentration typically present in humans with diabetes." (PMID 18167556, 2008). "Additionally, UCP2 gene polymorphisms are associated with both diabetes and PDAC, with UCP2 loss significantly reducing oncogenic Kras-induced PDAC growth." (PMID 40427173, 2025). "In the case of diabetes, UCP2 protects pancreatic β-cells from oxidative stress and glucotoxicity." (PMID 39920720, 2025). "It is hypothesized that in type 2 diabetes mellitus pathogenesis, oxidative stress induces the expression of UCP2, resulting in reduced ATP synthesis in beta cells that results in slower insulin response to glucose levels." (PMID 39561140, 2024). "Since UCP2 plays a role in reducing ROS production, the selective activation of UCP2 may have therapeutic potential in patients with diabetes." (PMID 36770960, 2023). "UCP2 may be a promising therapeutic target for treating type 2 diabetes mellitus because it regulates insulin secretion and beta-cell dysfunction." (PMID 36770960, 2023). "It remains unclear how UCP2 affects the development of diabetes, yet some research groups have used either UCP2-overexpressing mouse islets or β-cell-specific UCP2-knockout mice." (PMID 35800776, 2022). "However, at the same time, UCP2 inhibits insulin secretion, which is manifested as an elevated content of ucp2 mRNA in rats with alloxan-induced diabetes vs. the diabetic group treated with SkQ1." (PMID 34829620, 2021). "In this study based on Chinese Han population in Beijing district, we selected 8 SNPs in the functional region of UCP2, and the results indicated that the alleles and genotypes were not significantly different between prediabetes/diabetes and control." (PMID 29849618, 2018). "UCP2 antioxidant role has even been indicated for rat retina in the early stages of diabetes." (PMID 29351723, 2018). "As UCP2 is widely expressed in many tissues such as liver, its antioxidant activity makes it logical to search look for benefits on diabetes through counteracting the oxidative stress appeared in diabetes and its complications." (PMID 29949946, 2018). "In addition, the expression of SIRT1 is significantly lowered and UCP2 increased in the liver of rats with diabetes and NAFLD." (PMID 29949946, 2018). "The effects of UCP2 polymorphisms on LTL in populations without diabetes have not been well described." (PMID 27615599, 2016). "Our aims are to evaluate the interaction between LTL and UCP2 polymorphisms in 950 subjects without diabetes." (PMID 27615599, 2016). "Our study findings demonstrate that the UCP2 rs659366 A allele is associated with longer LTL in a rural population without diabetes or pre-diabetes." (PMID 27615599, 2016).
diabetes (continued). "In this study, we investigated whether UCP2 -866G/A, Ala55Val and Ins/Del polymorphisms were associated with DKD in patients with type 2 diabetes mellitus (T2DM), and whether they had an effect on UCP2 gene expression in human kidney tissue biopsies." (PMID 26218518, 2015). "On the one hand, upregulation of UCP2 in adipose tissue or kidney could reduce ROS production and relieve diabetes or relevant complication; but on the other hand, increased UCP2 in islet β-cells was related to reduction of insulin secretion." (PMID 24669227, 2014). "Nevertheless, several studies indicated that UCP2 could have deleterious effects on cellular function, like in the development of insulin resistance and the pathogenesis of type 2 diabetes mellitus." (PMID 24945157, 2014). "The relationship between UCP2 and diabetes mellitus was complex." (PMID 24669227, 2014). "Several gene polymorphisms of UCP1, UCP2, and UCP3 were reported to be associated with diabetes." (PMID 23841103, 2013). "The explanation for the discrepancy between kidney and whole-body regulation of oxidative stress in diabetes may relate to specific role of UCP-2 in the kidney." (PMID 22768304, 2012). "This investigation suggested that in addition to stimulation of insulin, genipin might protect the integrity of podocyte and delay the onset of DN through inhibition of UCP2 protein expression in diabetes." (PMID 22848482, 2012). "We speculate that ANT compensates for decreased UCP-2 function to protect the mitochondria from excessive diabetes-induced oxidative stress." (PMID 22768304, 2012). "A variant in the promoter of the human uncoupling protein 2 (UCP2) gene, the G-866A polymorphism, has been associated with future risk of coronary heart disease events, in those devoid of traditional risk factors and in those suffering from diabetes." (PMID 19527523, 2009). "Data coming from rodents models and animal experiments support the idea that changes in UCP2 expression and/or activity could contribute to beta cell dysfunction and to the pathogenesis of diabetes." (PMID 19065272, 2008). "This increased UCP-2 expression in the presence of glucose was further amplified by 50% by addition of the actively oxidized fatty acid oleic acid to human islets at a concentration typically present in diabetes (∼0.45 mM)." (PMID 18167556, 2008). "Increased UCP2 results in β-cell dysfunction, impaired insulin sensitivity, and earlier, more severe diabetes, but may protect from diabetic neuropathy." (PMID 16968550, 2006). "Body size, diabetes mellitus, and insulin resistance have been linked to chromosome 11; this region also contains several candidate genes, including insulin (OMIM 17673), SHIP2 (OMIM 600829), and the uncoupling protein 2 (OMIM 601693)." (PMID 14975167, 2003). "Besides the oxidative stress regulatory effects of the UCP2, toxicants pose their harms through the down-regulation of UCP2 and may lead to diabetes mellitus (DM)." (PMID 39916822, 2025). "We also analyzed the correlation betweenUCP1, UCP2, andUCP3mRNA expression and laboratory parameters (serum levels of total cholesterol, triglycerides, LDL-C, and HDL-C) and clinical parameters comprising the main factors associated with CAD (hypertension, diabetes, and body mass index)." (PMID 36651711, 2023). "However, a compensatory increase in ANT activity after the inhibition of UCP2 using small interfering RNA has been previously demonstrated in diabetes, which resulted in increased mitochondrial leak respiration, decreased mitochondria membrane potential, and decreased oxidative stress." (PMID 38188249, 2023). "Therefore, inhibition of UCP2 or AldB might be a promising therapeutic strategy to improve insulin secretion in patients with diabetes." (PMID 35800776, 2022).
diabetes (continued). "The association between the UCPs genes and diabetes has been investigated by many studies, and the most often studied SNPs are the rs1800592 (−3826A/G) of the UCP1 gene, the rs659366 (−866G/A), rs660339 (Ala55Val), and Ins/Del of the UCP2 gene, and the rs1800849 (−55C/T) of the UCP3 gene." (PMID 32028915, 2020). "Our aims are to determine genetically whether there is an interaction between underlying LTL and UCP2 polymorphisms in the absence of diabetes and pre-diabetes." (PMID 27615599, 2016). "Moreover, increased UCP2 expression has been implicated in limiting stimulus-secretion coupling in β-cells in some animal models of diabetes but not in others." (PMID 19956695, 2009). "Activation of UCP2 and COX in 45-day diabetic mitochondria seems to be a response to the diabetes process that leads to more efficient handling of ROS." (PMID 25951172, 2015). "Diabetes resulted in increased UCP-2 protein expression and UCP-2-mediated uncoupling, but normal mitochondria membrane potential." (PMID 22768304, 2012). "Based on these findings, we postulated that FG-4592 could exert a cardioprotective effect in diabetes by reducing oxidative stress injury through the enhancement of HIF-1α and UCP2 expression." (PMID 39920720, 2025). "The case-control study comprised 385 patientswith type 1 diabetes mellitus (T1DM): 223 patients without DKD and 162 with DKD.UCP2 -866G/A (rs659366) and Ins/Del polymorphisms weregenotyped by real-time PCR and conventional PCR, respectively." (PMID 31479096, 2020). "Due to the close correlation between these proteins (SIRT and UCP) and mitochondrial oxidative phosphorylation, we hypothesized that M. oleifera may exert a protective effect against the development of diabetes through regulatory effect of SIRT3 and UCP2." (PMID 29949946, 2018). "Otherwise, protein levels of mitochondrial respiratory complex (CI‐IV), ATP synthase and UCP2 content were not altered with diabetes but decreased with aging." (PMID 26847727, 2016). "We demonstrate that UCP2 rs659366 A allele and rs660339 T allele are both related to longer LTL in subjects without diabetes, independent of cardiovascular risk factors." (PMID 27615599, 2016). "The progress in the role of UCP1, UCP2, and UCP3 on diabetes mellitus is summarized in this review." (PMID 23841103, 2013). "Diabetic kidneys had increased transcript and membrane-bound protein levels of Nox4, the renal-specific generator of cytosolic reactive oxygen species (ROS) and reduced expression of SOD2, UCP2, GPX3, NQO1, and CAT." (PMID 23149823, 2013). "Genipin, a natural compound found in Gardenia jasminoides, selectively inhibits uncoupling protein 2 (UCP2)-mediated proton leak across the mitochondrial inner membrane and has been used in traditional Chinese medicine for centuries in the context of treatment of diabetes, cancer, and inflammation." (PMID 41300438, 2025). "This study suggests that the role of UCP2 in blood glucose regulation and diabetes may not be concentration-dependent." (PMID 39707176, 2024). "Thus, UCP2 rs659366 A allele and rs660339 T allele are both related to longer LTL in subjects without diabetes, independent of cardiovascular risk factors." (PMID 27615599, 2016). "Thus, we suggest that diabetes risk due to a −866G/G genotype is unlikely to influence our primary associations and models with LTL and UCP2 genotypes." (PMID 27615599, 2016). "However, it seems that UCP2 mRNA expression in the kidney was unaffected after diabetes in the presence or absence of genipin." (PMID 22848482, 2012). "While UCP2 concentration is very low or absent in most normal tissues it has been found to be more highly expressed in aging vs. young fibroblasts, in pancreatic islets in type 2 diabetes mellitus, and in macrophages under inflammatory stimulation." (PMID 19480693, 2009).